TNNC1 (troponin C1, slow skeletal and cardiac type)
Diseases named in the same sentence as TNNC1 in open-access papers (continued):
Sharing a sentence is not in itself a finding about the gene and the disease.
tumor (8 papers, 2017 to 2026). "These genes were consistently dysregulated in LUAD samples across cohorts (p < 0.05) and correlated distinctly with immune cell infiltration: TNNC1 was associated with anti-tumor immunity, while the others linked to immunosuppressive cells." (PMID 41671296, 2026). "This study assessed whether TNNC1 affects LUAD biological functions through M2 tumor-associated macrophage (TAM) polarization." (PMID 40433361, 2025). "In addition, TNNC1 is aberrantly expressed in multiple cancers, and the disruption of TNNC1 expression is associated with tumorigenesis, particularly tumor cell invasion." (PMID 39494275, 2024). "Likewise, we found a strong association between the abnormal expression of TNNC1 and the tumor immune microenvironment." (PMID 39494275, 2024). "Recent evidence suggests troponin family members exhibit abnormal expression in various tumors, with TNNC1 specifically demonstrating tumor-suppressive properties in certain cancer types." (PMID 40433361, 2025). "In future investigations, we will perform TNNC1 knockdown, Transwell cell migration, scratch, and cell-counting kit 8 assay experiments to examine the inhibitory effect of siTNNC1 on tumor cell migration and proliferation." (PMID 39494275, 2024). "Although some troponin complex members are overexpressed in several cancer types, a recent study clearly proved the tumour suppressor activity of TNNC1." (PMID 38528259, 2024). "TCGA database analysis revealed that E2F7, CD82, and TNNC1 showed significantly higher expression in tumor tissues than in normal tissues." (PMID 36612299, 2023). "Downregulation of TNNC1 (Troponin C1) expression accelerated tumor formation and increased mortality in LUAD patients." (PMID 34987577, 2021). "The combined presence of TNNC1+ and M2+ exacerbates the adverse impact on LUAD patient survival, suggesting that TNNC1 not only affects disease progression through direct action on tumor cells but also exerts indirect influence by regulating the tumor immune microenvironment." (PMID 40433361, 2025). "Our study focuses on TNNC1 as a key tumor suppressor gene in LUAD." (PMID 40433361, 2025). "Furthermore, through eight machine learning models, we identified TNNC1 as a key tumor suppressor gene in LUAD." (PMID 40433361, 2025). "Similarly, downregulated TNNC1, a novel finding in LUAD, is associated with extended survival, suggesting potential tumor-suppressive functions." (PMID 40433361, 2025). "In conclusion, our study indicated the complex function of TNNC1 as a key tumor suppressor gene in LUAD, not only participating in the regulation of tumor cell proliferation and apoptosis but also in tumor microenvironment shaping and drug resistance development." (PMID 40433361, 2025). "IHC staining indicated higher TNNC1 expression levels in tumor samples." (PMID 39494275, 2024). "On the other hand, Troponin C (TNNC1), a member of the troponin complex which may exert tumour suppression activities, was found to be down-regulated in the engineered cells." (PMID 38528259, 2024). "TNNC1 was also validated as a tumor suppressor, which is downregulated in LUAD patients." (PMID 36067196, 2022). "We confirmed through machine learning residual analysis that TNNC1 is significantly downregulated in LUAD tissues, consistent with its function as a tumor suppressor gene." (PMID 40433361, 2025). "Additionally, TNNC1 may indirectly regulate macrophage polarization by influencing interactions between tumor cells and macrophages, for example, by regulating the cytokine spectrum secreted by tumor cells or by affecting the expression of cell surface molecules." (PMID 40433361, 2025). "At the molecular level, TNNC1 may participate in macrophage polarization through the following mechanisms: First, as a calcium metabolism-related protein, TNNC1 may regulate calcium signaling in the tumor microenvironment, thereby affecting macrophage differentiation and polarization." (PMID 40433361, 2025).
tumor (continued). "TNNC1 was an effector protein of MFAP5 in stomata, which promoted cell motility and invasion potential via tumor-stroma crosstalk and subsequently affected clinical outcomes." (PMID 27713166, 2017). "Our research significantly expands the understanding of TNNC1’s role in LUAD, particularly by revealing the association between TNNC1 and EGFR-TKI resistance and tumor-associated macrophage polarization, areas not explored in previous studies." (PMID 40433361, 2025).
cancer (5 papers, 2018 to 2025). A tumor composed of atypical neoplastic, often pleomorphic cells that invade other tissues. "Moreover, as already noted, mutations in the TNNC1 gene are associated with certain cancers in the COSMIC database." (PMID 29416706, 2018). "We observed that TNNC1 is highly expressed in erlotinib resistance datasets, a finding consistent with the pattern proposed in previous studies where genes associated with drug resistance often exhibit low expression in cancer tissues but high expression in resistant cells." (PMID 40433361, 2025). "A similar mechanism may exist in EGFR-TKI resistance, where upregulated TNNC1 may promote cancer cell survival by enhancing autophagic flux, thereby conferring resistance to EGFR-TKIs such as erlotinib." (PMID 40433361, 2025). "Furthermore, the genes encoding cTnC (TNNC1; Id: COSG56773), fsTnC (TNNC2; Id: COSG65631), and all three TnT isoforms (TNNT1, Id: COSG65275; TNNT2, Id: COSG67007; TNNT3, Id: COSG60869) are overexpressed in several cancer types according to the COSMIC database." (PMID 29416706, 2018). "However, our focus in this study was not on the functional alterations of TNNC1 and calcium channels, as our primary objective was to evaluate the anticancer efficacy of bepridil and the changes in cancer-related phenotypes." (PMID 37511982, 2023).
infection (1 paper, 2023). The state of being infected such as from the introduction of a foreign agent such as serum, vaccine, antigenic substance or organism. "Similar results were obtained for non-infection associated TashAT2 modulated candidates, with higher expression confirmed for sulphatase 1 (SULF1), Lanthionine synthase C-like protein 3 (LANCL3) and troponin (TNNC1)." (PMID 37276213, 2023).
TNNC1 also shares sentences with these, for which no sentence is quoted: ventricular fibrillation (3 papers); atrial fibrillation (2); cardiovascular diseases (2); diabetic cardiomyopathy (2); Duchenne muscular dystrophy (2); heart failure (2); adenocarcinoma (1); asymmetrical septal hypertrophy (1); breast carcinoma (1); cardiac arrest (1); cardiac sarcomas (1); chronic kidney disease (1); embryonal carcinoma (1); familial hypertrophic cardiomyopathy (1); head and neck squamous cell carcinoma (1); Hearing impairment (1); heart disease (1); myocarditis (1); Obesity (1); restrictive cardiomyopathy (1); sarcoma (1); squamous cell carcinoma (1); Wilms tumor (1).